ADORA2B (adenosine A2b receptor)
Description:
Receptor for adenosine. The activity of this receptor is mediated by G proteins which activate adenylyl cyclase.
Synonyms: ADORA2
Tractability: Small molecule: an approved drug acts on it; a structure with a bound ligand is known; a high-quality ligand is known; it belongs to a druggable protein family. Antibody: its Gene Ontology location is reachable by antibodies, with high confidence; UniProt places it where antibodies can reach, with medium confidence; UniProt predicts a signal peptide or a membrane-spanning region. PROTAC: ubiquitination databases record sites on it; a small molecule that binds it is known.
Target class: Family A G protein-coupled receptor; Membrane receptor; Small molecule receptor (family A GPCR); Adenosine receptor; Nucleotide-like receptor (family A GPCR)
Chemical probes: CHEMBL1490082, MRS 1754 (high quality)
Safety:
Unwanted effects reported when the protein is acted on. In parentheses: how it was acted on, where the effect was seen, and who reports it.
decreased pain (inhibition, acute dosing; immune, peripheral nervous system; source: Lynch et al. (2017))
increased/decreased inflammation (activation, acute dosing and inhibition, acute dosing; immune, peripheral nervous system; source: Lynch et al. (2017))
Gene: Protein-coding gene on chromosome 17 (15,945,130 to 15,975,746, forward strand). Ensembl gene ENSG00000170425.
Subcellular location: Cell membrane
Subcellular location (Human Protein Atlas): Plasma membrane; Primary cilium tip; Vesicles
Pathways (Reactome):
Signal Transduction: Adenosine P1 receptors; G alpha (s) signalling events
Disease: ADORA2B mediated anti-inflammatory cytokines production
Metabolism of proteins: Surfactant metabolism
Gene Ontology:
Molecular function: protein binding; G protein-coupled adenosine receptor activity; G protein-coupled receptor activity
Biological process: activation of adenylate cyclase activity; adenylate cyclase-activating G protein-coupled receptor signaling pathway; G protein-coupled receptor signaling pathway; vasodilation; G protein-coupled adenosine receptor signaling pathway; presynaptic modulation of chemical synaptic transmission
Cellular component: plasma membrane; glutamatergic synapse; membrane; presynapse; Schaffer collateral - CA1 synapse; synapse
Genetic constraint (gnomAD): Loss-of-function variants: 22 observed, 22.25 expected, observed/expected ratio (o/e) 0.99, 90% interval 0.71 to 1.41. The upper end of that interval is the gene's LOEUF score, 1.41, which puts it in group 5 of 6, group 1 being the genes least tolerant of losing a copy. Missense variants: 441 observed, 419 expected, observed/expected ratio (o/e) 1.05, 90% interval 0.97 to 1.14. Synonymous variants: 179 observed, 172.95 expected, observed/expected ratio (o/e) 1.03, 90% interval 0.92 to 1.17.
Homologues: Orthologues: chimpanzee ADORA2B (99% identical), macaque ADORA2B (97% identical), rabbit ADORA2B (93% identical), mouse Adora2b (88% identical), rat Adora2b (86% identical), pig ADORA2B (81% identical), tropical clawed frog adora2b (63% identical), zebrafish adora2b (62% identical), guinea pig ADORA2B (60% identical), Drosophila melanogaster AdoR (33% identical). Paralogues in human: ADORA2A (58% identical), ADORA1 (45% identical), ADORA3 (37% identical).
Diseases named in the same sentence as ADORA2B in open-access papers:
ADORA2B is named in the same sentence as 96 diseases in open-access papers, as found by Europe PMC text mining. Sharing a sentence is not in itself a finding about the gene and the disease. The quoted sentences say what the papers report.
breast carcinoma (12 papers, 2015 to 2025). "Consistent with this, for ADORA2B (encoding the Adenosine receptor A2B), we have previously shown that its inhibition, either genetically or pharmacologically, strongly impairs lung colonization of breast cancer cells." (PMID 28411283, 2017). "Among these adenosine receptors, A2BR (encoded by ADORA2B gene) expression and activation of its downstream signaling pathway has been shown to promote breast cancer metastasis 26,27, and genetic inhibition of A2BR blocks lung metastasis of TNBC in a xenograft mouse model." (PMID 35401817, 2022). "Conversely, in breast cancer, Adora2b modulates CAFs, enhancing metastasis via homodimers in high-adenosine TMEs." (PMID 41346607, 2025). "Adenosine signaling through Adora2b in breast cancer cells regulates the tumor microenvironment and enhances pro-tumorigenic actions in cancer-associated fibroblasts, effects correlated with increased metastatic potential and poor prognosis." (PMID 37187740, 2023). "A recent report indicates that hypoxia-inducible factor 1-dependent expression of ADORA2B facilitates breast cancer stem cell enrichment." (PMID 35140786, 2022). "ADORA2B was highly expressed in breast cancer patients in general, as well as in TNBC patients (29.3% (68/232), and 39.4% (26/66), respectively)." (PMID 30349649, 2018). "For example, as we and others have shown previously, pharmacological inhibition of the adenosine receptor ADORA2B strongly inhibits breast cancer in mice, as do monoclonal antibodies directed against PTP4A1 (PRL1)." (PMID 28411283, 2017). "We and others have shown that Fra-1 promotes metastasis through various molecules: ADORA2B in breast cancer, MMPs in breast cancer and in lung epithelial cells, CD44 in mesothelioma, AXL in bladder cancer, FAK and EZH2 in colon cancer." (PMID 26646695, 2015). "These discrepancies may also involve tissue-specific receptor dimerization: Adora2b-Adora2a heterodimers in ovarian cancer blunt pro-tumor effects, while Adora2b homodimers predominate in GC and breast cancer, amplifying signaling." (PMID 41346607, 2025). "In summary, the findings from this study are consistent with ADORA2B activity being important for tumor progression in at least a subset of breast cancer, providing a potential therapeutic target for the development of small molecule inhibitors for the treatment of this devastating disease." (PMID 30349649, 2018). "Nevertheless, we note that FRA1-promotion of cell migration likely involves other AP-1 target genes such as MMPs and adenosine receptor A2B (ADORA2B) as described in breast cancer, uPA in colon carcinoma, receptor tyrosine kinase AXL in bladder cancer, and CD44 and c-Met in mesothelioma." (PMID 27144339, 2016). "However, despite these promising results in melanoma, breast cancer, and gastric cancer cells, the specific role of Adora2b in metastatic development remains unknown." (PMID 37187740, 2023). "Importantly, we have demonstrated that ADORA2B may play a critical role in the progression (proliferation and metastasis) of breast cancer." (PMID 30349649, 2018). "The expression of Adora2b and its subsequent activation was shown to be elevated by HIF-1α in hepatic ischemia-reperfusion injury mouse models, acute lung injury, liver cancer, and breast cancer." (PMID 37187740, 2023).
pulmonary fibrosis (8 papers, 2018 to 2023). Chronic progressive interstitial lung disorder characterized by the replacement of the lung tissue by connective tissue, leading to progressive dyspnea, respiratory failure, or right heart failure. "Regarding the ADORA2B mediated mechanisms, our data showed that activation of ADORA2B in PASMCs leads to increased levels of IL-6 and hyaluronan, two mediators that have been associated in the pathophysiology of lung fibrosis and PH." (PMID 29910735, 2018). "ADORA2B contributes to pulmonary fibrosis and pulmonary hypertension associated with COPD42–44." (PMID 33658578, 2021). "In more detail, HLA-DPB1 is a known COPD gene related to disease severity, SERPINA6 was associated with emphysema, a deletion in ADORA2B was shown to be associated with a decrease in lung fibrosis and pulmonary hypertension, and ELMOD2 is a candidate gene for familial idiopathic pulmonary fibrosis." (PMID 30845926, 2019). "Interestingly, we also show that activation of Adora2b modulates expression of Tgm2, a multifunctional enzyme that has been associated with PH and pulmonary fibrosis." (PMID 29910735, 2018). "ADORA2B was known to be the major regulator of the formation of lung myofibroblasts and the development of lung fibrosis." (PMID 37644529, 2023). "Further exploring the molecular mechanisms of Dex modulating ADORA2B expression in pulmonary fibrosis will be of interest." (PMID 37644529, 2023). "Here, we firstly demonstrate the relationship between Dex and ADORA2B in pulmonary fibrosis and found that Dex significantly decreased the expression of ADORA2B in lung myofibroblasts in vitro and in experimental pulmonary fibrosis models." (PMID 37644529, 2023). "Altogether, these data suggested that Dex strongly inhibits experimental pulmonary fibrosis via regulating ADORA2B in vivo." (PMID 37644529, 2023). "We next used our BLM-induced model of lung fibrosis and PH to evaluate the effect of conditional deletion of Adora2b in vascular smooth muscle cells in a model mimicking features of Group III PH." (PMID 29910735, 2018). "Zhigang Zhang group reported that Multi-walled carbon nanotube (MWCNT)-induced lung fibrosis facilitated lung myofibroblasts differentiation in an ADORA2B-dependent manner, and the ADORA2B antagonist CVT-6883 significantly reduced the lung fibrosis degree in MWCNT-treated mice." (PMID 37644529, 2023). "Furthermore, Dex inhibits myofibroblast differentiation and pulmonary fibrosis via downregulating ADORA2B expression." (PMID 37644529, 2023). "Moreover, the role of ADORA2B in Dex suppressing myofibroblast differentiation and pulmonary fibrosis was determined using the ADORA2B agonist BAY60-6583." (PMID 37644529, 2023). "Emerging evidence supports ADORA2B as the major regulator of the trajectory of pulmonary fibrosis." (PMID 37644529, 2023). "Moreover, Dex inhibits myofibroblast differentiation and pulmonary fibrosis via downregulating ADORA2B expression." (PMID 37644529, 2023). "Dex may alleviate lung fibrosis and myofibroblast differentiation through the ADORA2B-mediated MAPK signaling pathway." (PMID 37644529, 2023). "An increased expression of ADORA2B was reported in combined pulmonary fibrosis and emphysema syndrome, and it was shown that the ADORA2B-mediated hyaluronan synthase-3 expression of macrophages led to hyaluronan accumulation, responsible for pulmonary hypertension in a mouse model." (PMID 34209651, 2021). "In line with this, we hypothesize that the hypoxic environment in ARDS leads to increased expression or activity of CD73 and ADORA2B such as in PH in the setting of lung fibrosis that leads to accumulation of adenosine and subsequent activation of ADORA2B." (PMID 33537342, 2020). "Michael R Blackburn and colleagues showed that ADORA2B antagonism could significantly downregulate proinflammatory cytokines and chemokines and alleviate lung fibrosis, suggesting that ADORA2B signaling plays a central part in pulmonary injury and fibrosis in vivo." (PMID 37644529, 2023).
pulmonary fibrosis (continued). "Thus, some of the differences in the findings about the roles of ADORA2A and ADORA2B in radiation-induced dermal and pulmonary fibrosis may well be due to the differences in the damage model." (PMID 31623231, 2019). "However, whether Dex affect pulmonary fibrosis largely via ADORA2B remains unknown." (PMID 37644529, 2023). "Experiments using the ADORA2B antagonist (GS-6201) or full Adora2b knock-out mice revealed that genetic deletion or pharmacological inhibition of Adora2b subdued both the fibrotic deposition and the development of PH in a mouse model of chronic bleomycin (BLM)-induced lung fibrosis and PH." (PMID 29910735, 2018).
melanoma (6 papers, 2015 to 2023). A malignant, usually aggressive tumor composed of atypical, neoplastic melanocytes. "In experimental mouse models of melanoma and triple-negative breast cancer metastasis, the incidence of metastasis is significantly decreased when mice are treated with an Adora2b antagonist." (PMID 37187740, 2023). "Furthermore, adenosine A2b receptor blockade could decrease VEGF secretion in melanoma cells to promote chemotherapy-induced apoptosis by impairing IL-8 production." (PMID 31897237, 2020). "The ADORA2B antagonist MRE 2029 F20 reduced ERK1/2 and Akt phosphorylation levels in melanoma cells in hypoxia." (PMID 26228921, 2015). "In contrast, some studies have reported that ADORA2B has no role in adenosine-induced proliferation of human melanoma cells." (PMID 26228921, 2015).
pulmonary hypertension (6 papers, 2015 to 2024). Increased pressure within the pulmonary circulation due to lung or heart disorder. "Interestingly, our results demonstrate that deletion of Adora2b from smooth muscle cells is able to prevent the development of pulmonary hypertension in two distinct experimental models of PH." (PMID 29910735, 2018).
lung injury (5 papers, 2018 to 2025). "Moreover, treatment with a specific agonist for the Adora2b is associated with a significant reduction in infarct sizes in murine or rat models of myocardial ischemia-reperfusion injury." (PMID 36009485, 2022). "Our study determined the mechanism of sevoflurane’s protective properties and investigated the link between sevoflurane and the impact of a functional Adora2b via HO-1 modulation during lipopolysaccharide (LPS)-induced lung injury." (PMID 35406657, 2022). "Taken together, our study suggests that epithelial Adora2b is important to mediate the protective role of extracellular adenosine in bleomycin-induced acute lung injury." (PMID 33778007, 2021). "Augmented ADORA2B levels have been reported in patients with IPF and COPD that are consistent with increased Adora2b levels in experimental models of chronic lung injury that also present with PH." (PMID 29910735, 2018). "Studies in mice indicate that HIF-dependent increases in extracellular adenosine production and signaling through the Adora2A or Adora2b adenosine receptor attenuate inflammation or promote alveolar fluid clearance, thereby dampening pulmonary edema during acute lung injury." (PMID 40526427, 2025).
ovarian carcinoma (5 papers, 2020 to 2025). A malignant neoplasm originating from the surface ovarian epithelium. "High Adora2b levels are associated with a better prognosis in patients with ovarian cancer." (PMID 37187740, 2023). "Thus, high expression of ADORA2B at early stages of ovarian cancer could be associated with good prognosis." (PMID 35562985, 2022). "In ovarian cancer, high Adora2b expression correlates with better prognosis, and its activation reduces cell migration —likely due to lower adenosine levels (reduced CD73 activity) limiting receptor activation." (PMID 41346607, 2025). "In vitro pharmacological activation of Adora2b in ovarian carcinoma cells reduced cell migration and actin stress fiber expression." (PMID 37187740, 2023). "Here, we investigated the role of the adenosine A2B receptor (A2BR) in ovarian carcinoma-derived cells’ (OCDC) properties." (PMID 35562985, 2022). "We analyzed if the expression level of the ADORA2B transcript (coding for A2BR) correlated with the surveillance probability of ovarian carcinoma patients using the Kaplan–Meier Plotter database (K-MPdb)." (PMID 35562985, 2022). "The first analysis correlated the expression level of the ADORA2B transcript with the survival rate of ovarian cancer patients (996 of low expression and 439 of high expression)." (PMID 35562985, 2022). "In colon, prostate, ovarian carcinoma, adenosine A2b receptor is expressed predominantly with respect to other adenosine receptors, which suggests that it may play a role in the pathogenicity and tumor progression." (PMID 31897237, 2020).
triple-negative breast carcinoma (5 papers, 2018 to 2025). An invasive breast carcinoma which is negative for expression of estrogen receptor (ER), progesterone receptor (PR), and human epidermal growth factor receptor 2 (HER2). "Similarly, genetic deletion of the Adora2b receptor in mouse and human triple-negative breast cancer cells reduces their metastatic capability in vivo, suggesting an important role for Adora2b in cancer metastasis." (PMID 37187740, 2023). "Triterpene glycosides Cuc A0-1 and Dj A were identified as novel antagonists of the adenosine A2B receptor (A2BAR), which is overexpressed in triple-negative breast cancer MDA-MB-231 cells." (PMID 41226366, 2025).
asthma (4 papers, 2007 to 2023). "Based on the information from the BiosQTL and OpenTarget Genetics databases, DNA methylation of the ADORA2B CpG site (cg07563400) may be genetically regulated by two Cis-meQTL, rs3925260 and rs12452624, which have been linked to lung function parameters and asthma, respectively." (PMID 33658578, 2021). "Adenosine A2B receptor antagonists are therefore being considered as novel therapies for asthma." (PMID 17474152, 2007). "The adenosine receptors (ADORA1, ADORA2A, ADORA2B, and ADORA3) have a promising therapeutic role in asthma and chronic obstructive pulmonary disease (COPD)." (PMID 35052792, 2022).
chronic lung disease (4 papers, 2018 to 2024). According to the definitions of the American and British Thoracic Societies, including pulmonary functional tests, X-rays, and CT scans for items such as fibrosis, bronchiectasis, bullae, emphysema, nodular or lymphomatous abnormalities. "Using an Adora2b antagonist and global Adora2b-deficient mice, we have shown that abrogation of this receptor reduces PH associated with chronic lung disease." (PMID 29910735, 2018). "Taken together, these results suggest that in CPFE, as in other chronic lung diseases, adenosine synthesis is increased, together with expression of its low-affinity receptor, ADORA2B." (PMID 31036697, 2019). "Instead, ADORA2B has been identified as a major pathologic driver in models of chronic lung disease." (PMID 31623231, 2019). "Studies from our group have demonstrated that both adenosine and its receptor ADORA2B are elevated in chronic lung diseases." (PMID 31036697, 2019). "Taken together, these observations advocate the use of an ADORA2B antagonist to treat chronic lung diseases." (PMID 31036697, 2019). "In the context of chronic lung disease, increased expression of ADORA2B has been observed in patients with COPD and IPF, although it is important to mention that protective effects of ADORA2B have been reported in acute lung injury settings." (PMID 29910735, 2018). "In these studies, increased activation of the adenosine A2B receptor (ADORA2B) was shown to enhance expression of the hyaluronan synthases (HAS), contributing to the pathophysiology of chronic lung disease." (PMID 31036697, 2019). "This phenomenon has been shown to be present in chronic lung diseases such as COPD and IPF, and our data from CPFE explanted lung tissue reveal evidence of purinergic remodeling consistent with increased ADORA2B expression." (PMID 31036697, 2019).